Y_RNA (Y RNA )
Gene: Miscellaneous RNA gene on chromosome 15 (64,111,458 to 64,111,569, reverse strand). Ensembl gene ENSG00000201071.
Homologues: Orthologues: chimpanzee Y_RNA (100% identical). Paralogues in human: RNY1 (86% identical), Y_RNA (86% identical), Y_RNA (85% identical), RNY1P5 (84% identical), Y_RNA (84% identical), Y_RNA (83% identical), RNY1P8 (82% identical), Y_RNA (82% identical), RNY1P7 (81% identical), Y_RNA (81% identical), RNY1P11 (80% identical), Y_RNA (80% identical), and 94 more.